MMP2 (matrix metallopeptidase 2)
Diseases named in the same sentence as MMP2 in open-access papers (continued):
Sharing a sentence is not in itself a finding about the gene and the disease.
lung carcinoma (continued). "In addition, S. thunbergii-derived fucoidan inhibits angiogenesis by downregulating MMP-2 activity and VEGF/hypoxia-inducible factor-1α (HIF-1α) signaling in HUVEC cells and inhibits lung cancer cell A549 migration and proliferation." (PMID 31041568, 2019). "Therefore, it is necessary to carefully observe changes in TIMP-1 levels in addition to MMP-2 and MMP-9 to analyze lung cancer migration in the microgravity environment." (PMID 31601869, 2019). "Following pretreatment with TGF-β, an inflammatory cytokine, exosomal-derived lnc-MMP2-2 was shown to promote the expression of matrix metalloproteinase-2 (MMP2), an important EMT marker, to regulate the dissemination of lung cancer cells through the vasculature." (PMID 31467934, 2019). "A novel molecular mechanism was shown that HAI-2 serves as a novel non-covalent inhibitor of plasmin and suppresses the protease-induced activations of pro-HGF, pro-TGF-β1 and MMP-2/9 as well as ECM degradation, leading to reducing lung cancer cell motility, EMT, and metastasis." (PMID 30765871, 2019). "Interestingly, Kim and colleagues found that tumour metastasis with high WSB-1 expression presented increased expression of MMP2 and MMP9 levels in patients with lung cancer." (PMID 29540773, 2018). "However, p65 siRNA treatment significantly reduced MMP2 expression, suggesting that HMGB1 accelerated the MMP2 expression via the NF-κB pathway to promote lung cancer migration and invasion." (PMID 29850505, 2018). "Similar regulatory patterns were observed in the expression of MMP9 and MMP2 mRNA by G-Rh2 in two lung cancer cell lines with or without being co-cultured." (PMID 29783929, 2018). "Fourthly, the biological mechanism of how MMP-2 and TIMP-2 modified the risk of lung cancer were not investigated in this study." (PMID 29113325, 2017). "Exogenous BTG3 protein suppresses the levels of MMP-2 and PAI-1 expression in lung cancer cells." (PMID 28407690, 2017). "Using a cut-off value of 1.479 ng/ml, the sensitivity, specificity, positive predictive value (PPV), and negative predictivevalue (NPV) for MMP-2 in the diagnosis of lung cancer were 75.0%, 62.5%, 70.1%, and 67.6%, respectively." (PMID 29113325, 2017). "The present study has demonstrated that MMP-2 and TIMP-2 were useful biomarkers for lung cancer." (PMID 29113325, 2017). "We observed that BALF MMP-2 and TIMP-2 were increased at early stage lung cancer." (PMID 29113325, 2017). "Most importantly, we observed that MMP-2 and TIMP-2 was increased in BALF even at early stage of lung cancer, implying that they might be served as early diagnosis biomarker." (PMID 29113325, 2017). "Measurement of MMP-2 and TIMP-2 in BALF might be helpful for differential diagnosis of primary lung cancer." (PMID 29113325, 2017). "On the basis of their lung-tumorigenesis promoting functions, the MMP members MMP-1, MMP-2, MMP-7, MMP-9 and MMP-10 may result promising biomarkers for lung cancer." (PMID 29207990, 2017). "Additionally, miR-29c suppresses lung cancer cell adhesion to extracellular matrix (ECM) and metastasis by directly inhibiting integrin β1 and MMP2 expression and by further reducing MMP2 enzyme activity." (PMID 27829234, 2016). "Similarly, overexpression of Bcl-XL in lung cancer cells increases PI3K and p38 mitogen-activated protein kinase (MAPK) activities, which subsequently induce MMP-2 expression via Akt." (PMID 26621844, 2016). "Our results indicated that basigin-2 could regulate the downstream molecules MMP-2, MMP-9 and VEGF expression and contributed to a promotion in migration, invasion and proliferation of lung cancer cells." (PMID 27042161, 2016). "Our results indicated that basigin-2 could regulate its downstream molecules MMP-2, MMP-9 and VEGF expression and promote migration, invasion and proliferation of lung cancer cells." (PMID 27042161, 2016).
lung carcinoma (continued). "In our in vitro study, we found that the ectopic expression of nuclear HDAC6 reduced the invasiveness of lung cancer cells, which may result from HDAC6-mediated deacetylation of NF-κB, which downregulated MMP2 expression." (PMID 26388610, 2015). "Besides the prevention of plectin siRNA, curcumin demonstrated its ability to inhibit the matrix metalloproteinase (MMP)-2 and 9 as well as VEGF in human lung cancer A549 cells in vitro." (PMID 25566531, 2014). "We also blocked MMP-2 and MMP-9 functions with MMP-2 and MMP-9 neutralizing antibodies, respectively, and found that astrocyte CM containing neutralizing antibodies reduced its ability to induce both breast and lung cancer cell invasion." (PMID 24324647, 2013). "According to our results, snail did not appear to have any effect on the expression of MMP2 or 9 in lung tumors although both of these factors surely act in concert with snail promoting in the spread of lung carcinomas." (PMID 23157169, 2012). "The gene expression level of VEGFA, PGF, and their receptors FLT1 and KDR as well as MMP-2 and the inhibitors TIMP-1 and TIMP-2 was significantly higher in lung cancer specimens compared to pneumothorax samples and biopsies from lung transplant patients (P < 0.001)." (PMID 22593690, 2012). "MMP-2 and MMP-9 plays a crucial role in tumor invasion and angiogenesis by mediating degradation of the extracellular matrix, and inhibition of MMP activity has been shown to suppress lung cancer metastasis." (PMID 22662257, 2012). "In addition, Skp2 overexpression induces the expression of matrix metalloproteinase (i.e. MMP-2, MMP-9) and invasion of lung cancer cells." (PMID 21386910, 2011). "Overexpression of MMPs, in particular gelatinase A (MMP-2), gelatinase B (MMP-9) and stromelysin-3 (MMP-11), is related to tumour progression and metastasis in solid tumours including gastric, colon and lung cancer." (PMID 12771921, 2003). "In contrast, although MMP-2 expression is elevated across all lung cancer tissues, it does not differ significantly between early- and advanced-stage tumors, among various histological types, between smokers and non-smokers, or between patients with and without brain metastases (all p > 0.05)." (PMID 40321254, 2025). "Additionally, Chemerin can upregulate pro-angiogenic factors such as VEGF-A, MMP-9, MMP-2, and S100A9 in neutrophils through the activation of the MEK/ERK signaling pathway, thereby facilitating tumor vascularization and bone metastasis in lung cancer." (PMID 38571500, 2024). "Importantly, we found that FFAR2KO A549 and FFAR2KO H1299 lung cancer cells exhibited the enhancement of cell migration, invasion, and colony formation induced by TLR2 and TLR3, along with increases in the production of CCL2, IL-6, and MMP2 cytokines." (PMID 37287005, 2023). "Previous studies have shown that simvastatin modulates the expression of MMP-2 and MMP-9 in lung cancer tissue, as well as in a human lung adenocarcinoma cell line, indicating that simvastatin may play a role in in the prevention and treatment of lung cancer." (PMID 36835197, 2023). "Once MMP-2 is active, it is released, while MMP-14 and TIMP-2 remain attached to the membrane; this event may explain the low levels of MMP-14 and TIMP-2 found in blood from lung cancer patients." (PMID 36213817, 2022). "Our results clearly highlight the importance of MMP9, of the two MMPs, in regulating the levels of proBDNF and mBDNF in lung cancer cell media and might be, in part, explained by previous reports showing that MMP2 is not able to convert proBDNF to Mbdnf." (PMID 34209215, 2021). "Furthermore, Gene 33 expression exhibits an inverse relationship with the expression of metalloproteases MMP-2 and MMP-9 in lung cancer cells, suggesting that it may inhibit EGF-induced invasion." (PMID 34206547, 2021).
lung carcinoma (continued). "We found that the MMP2 was highly expressed in lung cancer tissues but not in adjacent normal tissues, suggesting that high expression of MMP2 might potentially related to lung cancer occurrence and development." (PMID 33115469, 2020). "b Expression of MMP2 did not relate to the histological type of lung cancer patients (p > 0.05)." (PMID 33115469, 2020). "Our results showing that TRPM7-mediated CSCs-like phenotype in lung cancer is modulated by Hsp90α/uPA/MMP2 signaling is therapeutically-relevant and partially consistent with recently demonstrated role of TRPM7 in the regulation of pancreatic cancer cell invasion through the Hsp90α/uPA/MMP2 pathway." (PMID 30477473, 2018). "To further verify the role of NDUFA4 in the growth and metastasis of lung cancer cells, we detected the expression of cell-growth-related molecules including CDK2, CDK3, CDK4, and CDK6, as well as metastasis-related molecules including CXCR4, E-Cadherin, MMP2, MMP3, and MMP9, respectively." (PMID 28325285, 2017). "Our study showed that NMI suppressed tumor growth by inhibiting PI3K/AKT, MMP2/MMP9, COX-2/PGE2 signaling pathways and p300-mediated NF-κB acetylation, and predicted a favorable prognosis in human lung adenocarcinomas, suggesting that NMI was a potential tumor suppressor in lung cancer." (PMID 29025423, 2017). "In the two COPD patients (out of 39), who were incidentally diagnosed with lung cancer metastasis, the levels of these serum biomarkers were determined [VEGF (2658.0, 1013.5 pg/ml), IL-8 (11.8, 23.7 pg/ml), MMP-9 (661.8, 1166.7 ng/ml) and MMP-2 (209.2, 95.7 ng/ml)]." (PMID 27811960, 2016). "Therefore, we hypothesized that miR-29c suppresses lung cancer cell adhesion to extracellular matrix (ECM) and metastasis by targeting integrin β1 and MMP2." (PMID 23936390, 2013). "Indeed, in this study we demonstrated that blocking ENO1 by treatment with an ENO1-specific Ab or suppressing ENO1 expression by treatment with a specific shRNA plasmid reduces plasmin and MMP2/9 activation, ECM degradation, and invasion capacity in lung cancer cells." (PMID 23894455, 2013). "MMP-2 is also upregulated in pathological conditions including cancer but like VEGFA is also elevated in normal processes including embryonic development and tissue remodelling so an increase in lung cancer specimens could be expected." (PMID 22593690, 2012). "Moreover, the MMP-1, MMP-2, MMP-9, and MMP-10 were found in the media of the ex vivo 3D lung model as well as in the serum of the blood samples collected from the superior vena cava and pulmonary veins of the lobectomy lung cancer specimens." (PMID 23028922, 2012). "Notably, FFAR2KO human lung cancer FFAR2KO A549 and FFAR2KO H1299 cells showed marked increases in cell migration, invasion, and colony formation in response to TLR2 or TLR3 stimulation, accompanied by elevations in NF-κB activation, cAMP levels, and the production of CCL2, IL-6, and MMP2 cytokines." (PMID 37287005, 2023). "Finally, the fact that A549 lung cancer cells were resistant to TGF-1-induced EMT, migration, and activation of MMP-2 suggests that kaempferol's antimetastatic effect may target essential components of numerous signaling pathways implicated in tumor metastasis." (PMID 35986346, 2022). "Moreover, an upregulation of APC and β-catenin was shown to significantly increase the levels of matrix MMP-9 and MMP-2 (members of the metalloproteinase family) expression and downregulate E-cadherin, Snail1, and Zeb1 expression, which ultimately resulted in EMT and bone metastasis in lung cancer." (PMID 34568020, 2021). "Another study showed that all lung cancer-derived exosomes, regardless of the cancer type (EGFR-mutated adenocarcinoma, wild-type adenocarcinoma, squamous cell lung cancer), induced an increase of the matrix metalloproteinase 2 (MMP2) activity in cells exposed to TEXs." (PMID 32825667, 2020).
lung carcinoma (continued). "Thus, to determine whether nano-EGCG has any effects on MMP-2 and MMP-9 in lung cancer cells, we first collected conditioned media of H1299 and CL1-5 cells treated for 24 hours with various concentrations of EGCG or nano-EGCG and analyzed the media through gelatin zymography assay." (PMID 32198390, 2020). "In lung cancer cells (A549), resveratrol (10 μM, 30 μM) decreased MMP-9 mRNA expression and activity and its promoter activity, without any significant impact on MMP-2." (PMID 39335164, 2024). "Expression of MMP1 (collagenase), MMP2 (gelatinase), and MMP3 (stromelysin) transcripts was not significantly altered in lung cancer cells co-cultured with MSCs, but all three transcripts were downregulated in MSCs after co-culture with lung cancer cells." (PMID 33119681, 2020). "In the present study, honokiol, an active compound from Magnolia officinalis plant, suppressed lung cancer cell migration and invasion via the inhibition of MMP‐9 activity, rather than MMP‐2." (PMID 32180962, 2020). "As expected, a significant positive correlation was found between the secretion of u-PA and MMP-2 and a significant negative correlation between u-PA and TIMP-2 secretion by NM treatment of lung cancer A-549 cells." (PMID 23563849, 2013). "MMP-2 concentrations were compared in two groups of controls, non-smokers (NSC) and smokers (SC), with three lung cancer subtypes, including adenocarcinoma (ADC), squamous cell carcinoma (SqCC), and other lung neoplasms (OLN), in relation to the MMP-2-735C/T genotype." (PMID 37445754, 2023). "We observed significant differences in the MMP-2 and MMP-9 concentrations between the -735CC and -735CT genotypes, as well as the -1562CC and -1562CT genotypes, respectively, not only among the lung cancer subtypes but also among the healthy non-smokers and smokers." (PMID 37445754, 2023). "In another lung cancer cell line A549, the anti-metastatic effect of CTD remained different as it only inhibited the gelatinous efficacy of MMP-2, but not MMP-9, while the expression level of either MMP-2 or MMP-9 had not changed." (PMID 32707651, 2020). "Importantly, G-Rh2 had a preference to decrease the expression levels of VEGF, MMP2, and MMP9 in co-cultured lung cancer cells, over than those in lung cancer cells without co-culturing." (PMID 29783929, 2018). "In addition, regardless of the fact that HIIE reduces the level of MMP2 in lung cancer tissues, it may promote the EMT of lung cancer cells." (PMID 35371324, 2022).
ovarian carcinoma (310 papers, 1999 to 2026). A malignant neoplasm originating from the surface ovarian epithelium. "Our results corresponded to findings in ovarian carcinoma cells, in which the upregulation of MMP2 mRNA expression was associated with enhanced peritoneal adhesion." (PMID 35954423, 2022). "The presence of AR associated with MMP-2 in the tumor cells was a risk factor for overall survival in epithelial ovarian cancer." (PMID 32718331, 2020). "Some studies have indicated that alterations in matrix metalloproteinase-2 (MMP-2) expression are often associated with overall metastatic potentials of many types of cancers, including breast, colorectal, and ovarian cancers." (PMID 31772330, 2020). "In contrast, high levels of MMP2 were found to be associated with a better chemotherapy response in ovarian cancer tissue." (PMID 32560557, 2020). "MMP2 (72 kDa type IV collagenase) is intimately linked with the invasion and metastasis of ovarian cancer, while MMP9 (68 kDa type IV collagenase) is a useful serum marker of ovarian cancer." (PMID 32083017, 2019). "Our previous studies found that RhoC expression was positively associated with many oncogenes in ovarian cancer, such as MMP2, BCL-xL and P70s6k." (PMID 28818073, 2017). "Our study found that high expression of the lncRNA ABHD11-AS1 in the ovarian cancer cell lines was associated with high expression of RhoC and its downstream molecules P70s6k, MMP2 and BCL-xL, while silencing of the lncRNA ABHD11-AS1 had the opposite effect." (PMID 28818073, 2017). "In ovarian cancer tissues and cultivated ovarian cancer cells, elevated αvβ6 expression is associated with the secretion of urokinase-type plasminogen activator (uPA), MMP-2, and MMP-9." (PMID 28869579, 2017). "Overexpression of MMP-2 in peritoneal implants of ovarian cancer cells is related to a significant risk of death." (PMID 28538838, 2017). "MMP-2 and -9 are particularly associated with the invasion of multiple gynecological maliginancies, such as cervical cancer, endometrial cancer and ovarian cancer." (PMID 27825139, 2016). "Another study demonstrated that tumor samples from ovarian cancer patients with greater biobehavioral risk had higher levels of MMP2+ and MMP9+ macrophage populations." (PMID 25738355, 2015). "MMP-2 and αv integrins were linked to ovarian carcinoma cell invasion of endothelial cells in vitro." (PMID 24194929, 2013). "MMP-9 and MMP-2 have been found consistently upregulated in ovarian cancer and are associated with poor prognosis." (PMID 23340649, 2013). "This may be due to the fact that the inflammatory microenvironment and extracellular matrix remodeling caused by TNF-αand MMP-2 in ascitic fluid of patients with ovarian cancer may be related to poor healing of intestinal anastomosis." (PMID 39931090, 2025). "Contrary to that, small number of mutations in MMP-2 and -11 genes increased the percentage of platinum resistant patients, suggesting that genetic alterations in TIMPs and MMPs shifts the platinum response status in ovarian cancer patients." (PMID 35047406, 2021). "Therefore, CQDs/Cu2O selectively mediated of ovarian cancer SKOV3 cells death mainly through decreasing the expression of MMP-2, MMP-9, F-actin, and VEGFR2, meanwhile CQDs/Cu2O caused apoptosis of SKOV3 via S phase cell cycle arrest." (PMID 33663548, 2021). "Moreover, the invasion of cancers such as breast, hepatoma, and ovarian cancer cells was markedly inhibited by baicalein by reducing matrix metalloproteinase (MMP)-2/-9 expression, associated with the MAPK signaling pathway." (PMID 35056061, 2021). "Mechanistically, LL-37 stimulates MSCs to secrete larger amounts of inflammatory and pro-angiogenic factors, such as IL-1 receptor antagonist, IL-6, IL-10, CCL5, VEGF, and MMP-2, and this phenomenon is closely associated with the promotion of ovarian cancer progression and metastasis." (PMID 30568223, 2019).